RN7SL126P (RNA, 7SL, cytoplasmic 126, pseudogene)
Gene: Miscellaneous RNA gene on chromosome 2 (85,567,662 to 85,567,960, reverse strand). Ensembl gene ENSG00000276281.
Homologues: Orthologues: chimpanzee Metazoa_SRP (99% identical), macaque Metazoa_SRP (95% identical). Paralogues in human: RN7SL1 (89% identical), RN7SL2 (88% identical), RN7SL3 (88% identical), RN7SL45P (86% identical), RN7SL122P (84% identical), RN7SL147P (84% identical), RN7SL493P (84% identical), RN7SL88P (84% identical), RN7SL679P (83% identical), RN7SL828P (83% identical), RN7SL186P (83% identical), RN7SL220P (83% identical), and 703 more.